SPACA7BP (SPACA7 family member B, pseudogene)
Synonyms: GC14
Gene: Transcribed unprocessed pseudogene on chromosome 13 (110,952,722 to 110,971,603, reverse strand). Ensembl gene ENSG00000275989.
Diseases named in the same sentence as SPACA7BP in open-access papers:
SPACA7BP is named in the same sentence as 1 disease in open-access papers, as found by Europe PMC text mining. Sharing a sentence is not in itself a finding about the gene and the disease.
SPACA7BP shares sentences with these, for which no sentence is quoted: cancer (1 paper).